TMEM107 (transmembrane protein 107)
Description:
Plays a role in cilia formation and embryonic patterning. Requires for normal Sonic hedgehog (Shh) signaling in the neural tube and acts in combination with GLI2 and GLI3 to pattern ventral and intermediate neuronal cell types (By similarity). During ciliogenesis regulates the ciliary transition zone localization of some MKS complex proteins.
Synonyms: MGC10744; JBTS29; MKS13; GRVS638; PRO1268
Tractability: Antibody: UniProt predicts a signal peptide or a membrane-spanning region.
Gene: Protein-coding gene on chromosome 17 (8,172,457 to 8,176,405, reverse strand). Ensembl gene ENSG00000179029.
Subcellular location: Membrane; Cell projection, cilium
Gene Ontology:
Molecular function: protein binding
Biological process: cilium assembly; non-motile cilium assembly; protein localization to ciliary transition zone; embryonic digit morphogenesis; neural tube patterning
Cellular component: ciliary transition zone; MKS complex; cilium; membrane
Genetic constraint (gnomAD): Loss-of-function variants: 18 observed, 17.85 expected, observed/expected ratio (o/e) 1.01, 90% interval 0.7 to 1.49. The upper end of that interval is the gene's LOEUF score, 1.49, which puts it in group 6 of 6, group 1 being the genes least tolerant of losing a copy. Missense variants: 152 observed, 187.86 expected, observed/expected ratio (o/e) 0.81, 90% interval 0.71 to 0.93. Synonymous variants: 68 observed, 76.64 expected, observed/expected ratio (o/e) 0.89, 90% interval 0.73 to 1.09.
Homologues: Orthologues: chimpanzee TMEM107 (100% identical), macaque TMEM107 (99% identical), dog TMEM107 (95% identical), pig TMEM107 (95% identical), guinea pig TMEM107 (94% identical), rabbit TMEM107 (94% identical), mouse Tmem107 (89% identical), zebrafish tmem107l (62% identical), rat Tmem107 (61% identical), zebrafish tmem107 (58% identical).
Diseases named in the same sentence as TMEM107 in open-access papers:
TMEM107 is named in the same sentence as 21 diseases in open-access papers, as found by Europe PMC text mining. Sharing a sentence is not in itself a finding about the gene and the disease. The quoted sentences say what the papers report.
ciliopathies (4 papers, 2017 to 2023). "Mutation or dysregulation of Cc2d2a, Tmem67, Kif7 plus Tmem107 and Topors, are known to cause ciliopathies." (PMID 30260431, 2018). "The protein TMEM107 has been previously implicated in ciliopathy-associated eye abnormalities." (PMID 37863656, 2023).
anencephaly (1 paper, 2022). A rare neural tube defect during pregnancy, resulting in the absence of a large portion of the brain and skull in the fetus. "In our case, the relationship between TMEM107 and anencephaly could not be investigated because the biological samples of the affected fetuses with anencephaly were not preserved." (PMID 35361766, 2022).
Anophthalmia (1 paper, 2023). Absence of the globe or eyeball. "Patients with TMEM107 pathological variants were diagnosed with a stronger phenotype in case of MKS with bilateral anophthalmia, and milder phenotypes with OFD and JBT with oculomotor apraxia and retinopathy, and OFD with strabismus." (PMID 37863656, 2023). "Moreover, it points to the fact that microphthalmia in Tmem107−/− animals is likely caused by down-regulated Pax6, whereas anophthalmia is rather caused by altered expression of Sox2." (PMID 37863656, 2023). "All examined Tmem107−/− mouse mutants manifested eye malformations including anophthalmia and microphthalmia." (PMID 37863656, 2023). "A mouse model lacking Tmem107 exhibited eye defects such as anophthalmia and microphthalmia, affecting retina differentiation." (PMID 37863656, 2023).
cyst (1 paper, 2023). A sac-like closed membranous structure that may be empty or contain fluid or amorphous material. "TMEM107 deficiency in retinal organoids resulted in the loss of primary cilia, down-regulation of retina-specific genes, and cyst formation." (PMID 37863656, 2023). "Liquid accumulation during the cyst initiation is usually caused by the altered function of gated channels, commonly present in ciliary membrane and at the ciliary base bordering with the TZ, where TMEM107 is localized." (PMID 37863656, 2023).
lung carcinoma (1 paper, 2022). "Another player, transmembrane protein 107 (TMEM107), whose function was previously unknown, was found to inhibit EMT and invasion in lung cancer through regulating the Hedgehog pathway." (PMID 35873564, 2022).
microphthalmia (1 paper, 2023). Congenital or developmental anomaly in which the eyeballs are abnormally small. "Mouse strains with mutations in Tmem107 demonstrate similar defects to human patients, including extra digits and a spectrum of craniofacial anomalies such as exencephaly, microphthalmia or skeletal defects in Tmem107schlei embryos." (PMID 37863656, 2023).
orofaciodigital syndrome (1 paper, 2023). Two syndromes of oral, facial, and digital malformations. "The TMEM107 locus has recently been found to be mutated in patients with Meckel–Gruber syndrome, Orofaciodigital syndrome, and Joubert syndrome." (PMID 37863656, 2023). "Patients who appear as homozygotes or compound heterozygotes for TMEM107 mutant allele have been diagnosed with Joubert (JS), Meckel–Gruber (MKS) or orofaciodigital syndrome (OFD)." (PMID 37863656, 2023).
TMEM107 also shares sentences with these, for which no sentence is quoted: Meckel syndrome 13 (2 papers); cannabis dependence (1); frontometaphyseal dysplasia (1); Joubert syndrome (1); Joubert syndrome 29 (1); Meckel syndrome, type 2 (1); Meckel-Gruber syndrome (1); Oculomotor apraxia (1); osteofibrous dysplasia (1); polydactyly (1); retinal diseases (1); retinopathy (1); spondylometaphyseal dysplasia (1); Strabismus (1).